VCAM1 (vascular cell adhesion molecule 1)
Diseases named in the same sentence as VCAM1 in open-access papers (continued):
Sharing a sentence is not in itself a finding about the gene and the disease.
endothelial dysfunction (continued). "Thus, we anticipated the level of s-ICAM-1 and s-VCAM-1 would be upregulated following EMPs treatment and may contribute to endothelial dysfunction." (PMID 28114372, 2017). "Moreover, endothelial dysfunction was further reflected by VCAM-1 expression on endothelial cells." (PMID 24472528, 2014). "In conclusion, prolonged intake of repeatedly heated palm oil appears to increase blood pressure in rats, which might be mediated by inflammation and endothelial dysfunction, as reflected by the adverse vascular remodelling and the induction of VCAM-1 expression on endothelial cells." (PMID 22778962, 2012). "Neurovascular integrity markers VCAM-1, ICAM-1, and VEGF were significantly elevated in diabetic rats, indicating endothelial dysfunction." (PMID 40723442, 2025). "Resistin is associated with various biological processes, including the proliferation of endothelial cells, angiogenesis, the expression of VCAM-1 and ICAM-1 in endothelial cells, and the generation of ROS, which contribute to endothelial dysfunction." (PMID 40943241, 2025). "Lefere and colleagues studied endothelial dysfunction in MASLD patients, identifying VCAM-1 as an independent predictor of significant fibrosis in this population." (PMID 40977717, 2025). "This endothelial dysfunction translates to increased monocyte adherence and vascular inflammation, as ImP upregulates ICAM‐1, VCAM‐1, and E-selectin, and correlates clinically with elevated soluble VCAM‐1 and CRP levels in patients with CAD." (PMID 41220438, 2025). "Surgery can induce endothelial dysfunction, leading to increased expression of adhesion molecules like ICAM-1 (Intercellular Adhesion Molecule-1) and VCAM-1 (Vascular Cell Adhesion Molecule-1) on endothelial cells." (PMID 40806279, 2025). "EMP, ADMA, VCAM-1 (Vascular Cell Adhesion Molecule-1), and ICAM-1 (Intercellular Adhesion Molecule-1) reflect endothelial dysfunction and vascular inflammation." (PMID 40949500, 2025). "Elevated endocan levels have been proposed not only as a biomarker but also as a mediator of endothelial dysfunction, via its regulation of ICAM-1/VCAM-1 expression and oxidative stress pathways." (PMID 40863140, 2025). "Cytokines such as TNF-α, IL-6, IL-17A, CXCL9, CXCL10, and VCAM-1 are often elevated in both MASLD and SAH, playing crucial roles in immune cell recruitment, endothelial dysfunction, and fibrogenesis." (PMID 40977717, 2025). "Endothelial dysfunction is frequently observed in CKD, with biomarkers such as asymmetric dimethylarginine (ADMA) and vascular cell adhesion molecule-1 (VCAM-1) shedding light on vascular health." (PMID 39473640, 2024). "Meanwhile, the increased mRNA expression levels of endothelial dysfunction markers, VCAM-1 and ICAM-1, were decreased in ISL-treated db/db mouse aortas, further confirming that ISL reverses T2D-induced endothelial dysfunction." (PMID 39339760, 2024). "Markers of inflammation (CRP, LDH, IL6), endothelial dysfunction (ICAM1, VCAM1, E-selectin), coagulation (fibrinogen) and fibrinolysis (D dimers) are used in assessing disease severity, prognosis and treatment options." (PMID 38474287, 2024). "One of the phenotypic features of endothelial dysfunction is the upregulation of cellular adhesion molecules (ICAM-1 and VCAM-1) and an increase in the expression of intercellular monocyte adherence to the endothelium." (PMID 39409189, 2024). "Based on these data, VCAM-1 concentration and ACE2 activity at ICU admission effectively reflected the degree of endothelial dysfunction." (PMID 38276214, 2024). "The overexpression of cell adhesion molecules (CAMs), including VCAM-1, ICAM-1, and E-selectin, in vascular endothelial cells is a phenotypic characteristic of endothelial dysfunction." (PMID 39065776, 2024).
endothelial dysfunction (continued). "Endothelial dysfunction is characterized by increased expression of cellular adhesion molecules such as ICAM-1 and VCAM-1." (PMID 39408198, 2024). "Encouragingly, ISL treatment significantly decreased the expression levels of VCAM-1 and ICAM-1 in db/db mouse aortas, further demonstrating that ISL reverses endothelial dysfunction in T2D mouse aortas." (PMID 39339760, 2024). "DA has an inhibitory effect on VCAM-1 expression in endothelial cells through the JNK pathway, and thus, can be used as a novel drug to improve endothelial dysfunction." (PMID 38998931, 2024). "The oxidative stress damages vascular endothelial cells, leading to endothelial dysfunction and increased expression of chemokines and adhesion molecules, including ICAM-1 and VCAM-1." (PMID 39452916, 2024). "Endothelial dysfunction is characterized by the overexpression of adhesion molecules, including intercellular adhesion molecule-1 (ICAM-1) and vascular cell adhesion molecule-1 (VCAM-1)." (PMID 39457107, 2024). "We showed endothelial dysfunction in cultured CiGEnCs evidenced by enhanced transcription and translaton of ICAM-1, VCAM-1, vWF, and ET-1 in response to Ang II stimulation to simulate the activated renin-angiotensin system in patients with malignant HTN." (PMID 37188751, 2023). "Endothelial dysfunction is characterized by the activation of endothelial cells and consequent upregulation of adhesion molecules on their surface, including ICAM-1 and VCAM-1." (PMID 37432255, 2023). "In human atherosclerotic lesions, endothelial cells have been shown to over-express intracellular VCAM-1, ICAM-1, and E-selectin in order to promote leukocyte adhesion and eventually stimulate endothelial dysfunction." (PMID 37112618, 2023). "Markers of endothelial dysfunction [plasma E-selectin, intracellular adhesion molecule 1 (ICAM-1) and VCAM-1] increased 2 h or/and 4 h after a high-AGEs meal compared with 2 h or/and 4 h after a low-AGEs meal." (PMID 37111220, 2023). "Endothelial dysfunction, an early phase of vascular inflammation in humans, commences with ICAM-1 and VCAM-1 expression and immune cell adhesion." (PMID 37382544, 2023). "In order to assess the contribution of inflammation as well as endothelial dysfunction, we first measured the serum levels of C-reactive protein (CRP) and Vascular Cell Adhesion Molecule-1 (sVCAM-1), respectively." (PMID 37398656, 2023). "VCAM1 is rarely expressed under physical conditions but could be quickly activated by a pro-inflammatory factor, including TNFα, which regulates the activation, maturation, and cytokine and chemokine release of leukocytes, thus playing a vital and direct role in endothelial dysfunction." (PMID 37841916, 2023). "Increased TMAO levels related to:– increased endothelial dysfunction,– decreased endothelial self-repairing ability,– increased adhesion of monocytes through activation of NF-κB/PKC/VCAM-1 pathway." (PMID 37337893, 2023). "Endothelial dysfunction suppresses eNOS activity and NO production while inducing the expression of adhesion molecules, such as ICAM-1, VCAM-1, and P-selectin, to promote the adhesion of monocytes and platelets to the endothelium." (PMID 38139268, 2023). "Endothelial dysfunction in KD by endothelial biomarkers (E-selectin, P-selectin,intercellular adhesion molecule-1 (ICAM-1), and vascular cellular adhesionmolecule-1 (VCAM-1)) was identified as early in 1992." (PMID 39076622, 2022). "The study also demonstrated homoarginine levels were inversely related to markers of endothelial dysfunction (e.g., ICAM-1 and VCAM-1)." (PMID 35722087, 2022). "PGN also triggers the up-regulation of vascular cell adhesion molecule-1 (VCAM-1) through the NOD1-RIP2-NF-κB axis, promotes the recruitment of myeloid cells, and leads to endothelial dysfunction." (PMID 35281098, 2022).
endothelial dysfunction (continued). "The protein expressions of endothelial dysfunction markers including ICAM-1 and VCAM-1 were upregulated in shFGA and HG groups, while CD31 and vWF were significantly downregulated." (PMID 35399949, 2022). "In addition, endothelial cell activation, mechanistically closely linked to endothelial dysfunction, is characterized by an upregulated expression of intracellular, vascular, and leukocyte adhesion molecules on the surface of endothelial cells (ICAM-1, ICAM-3, VCAM-1, E-selectin)." (PMID 35883760, 2022). "The proinflammatory vascular adhesion molecules VCAM-1 and ICAM-1 are biomarkers of endothelial dysfunction." (PMID 36432506, 2022). "TNF-α is reported to trigger the interaction between monocytes and vascular endothelial cells, enhance the expression of adhesion molecules, such as VCAM-1, ICAM-1, and E-selectin, and finally induce endothelial dysfunction." (PMID 36278191, 2022). "Evidence has shown that vascular cell adhesion molecule 1 (VCAM-1), tumor necrosis factor alpha (TNF-α), and VEGF-A are closely related to vascular lesions, especially VCAM-1, which is a biomarker of endothelial dysfunction." (PMID 36448064, 2022). "The adhesion molecules expressed by the endothelium, such as intercellular adhesion molecule-1 (ICAM-1) and vascular cell adhesion molecule-1 (VCAM-1), are widely accepted biomarkers of endothelial dysfunction." (PMID 34198968, 2021). "EVs derived from inflamed endothelium of clinically obese individuals have been shown to increase VCAM-1 production in HUVECS and to enhance leukocyte attachment in vitro, which supports endothelial dysfunction." (PMID 33924982, 2021). "eNOS downregulation and MCP-1, VCAM-1 and ICAM-1 upregulation with subsequent macrophage accumulation provided compelling evidences on HFHF induced endothelial dysfunction and activation that were also observed in OxLDL treated- and HSP60 overexpressing-HUVEC." (PMID 33441791, 2021). "Along with soluble adhesion molecules such as E-selectin and vascular cell adhesion molecule 1 (VCAM-1), ICAM-1 represent a molecular marker of endothelial dysfunction." (PMID 33924229, 2021). "The presence of endothelial dysfunction in preeclampsia has been well established, which was confirmed in our cohort by increased expressions of the endothelial dysfunction markers, VCAM-1 and ICAM-1 (VCAM-1: P < 0.01; ICAM-1: P ˂ 0.001; n = 3)." (PMID 32617576, 2021). "The phenotypic features of endothelial dysfunction include the upregulated expression of endothelial leukocyte adhesion molecules (ELAMs) [E-selectin, ICAM-1 and VCAM-1]." (PMID 33868242, 2021). "Endothelial dysfunction as measured by reflection index (RI), biomarkers of oxidative stress (NO, MDA, and glutathione), and inflammation (hsCRP, endothelin-1, ICAM-1, and VCAM-1) were evaluated at baseline, 4, and 12 weeks." (PMID 34257675, 2021). "We measured the levels of high-sensitivity C-reactive protein (hs-CRP), intercellular adhesion molecule 1 (ICAM-1), and vascular cell adhesion molecule 1 (VCAM-1) as markers of inflammation and endothelial dysfunction." (PMID 32433661, 2020). "Furthermore, circulating omentin-1 concentrations are associated with endothelial dysfunction in patients with impaired glucose tolerance by inhibiting the NADPH oxidase activity and enhancing the TNF-induced vascular cell adhesion molecule 1 (VCAM1) expression." (PMID 31694146, 2019). "The addition of synthetic peptides to human endothelial cells significantly prevents the expression of genes related to endothelial dysfunction and inflammation (eNOS, ICAM-1, VCAM-1, IL-6) and lowers NF-κB activation (all p < 0.05)." (PMID 31466215, 2019). "An increased concentration of biochemical markers of endothelial dysfunction, such as inter-cellular adhesion molecule 1 (ICAM-1), vascular cell adhesion protein 1 (VCAM-1) and E-selectin, were observed in hypertensive patients with LVH." (PMID 31447695, 2019).
endothelial dysfunction (continued). "The levels of such markers of endothelial dysfunction (PAI-1, ADMA, VCAM-1, and ICAM-1) have also shown to be higher in PCOS patients as compared with controls." (PMID 31456040, 2019). "Vascular cell adhesion molecule 1 (VCAM-1), a biomarker of endothelial dysfunction, appears to be an important mediator in inflammatory processes." (PMID 30535754, 2019). "Endothelial dysfunction is marked by the upregulation of cellular adhesion molecules, such as ICAM-1 and VCAM-1, that cooperate with chemokines and mediate the adhesion of mononuclear and neutrophil leucocytes." (PMID 31391047, 2019). "The connection with endothelial dysfunction is also supported by the observation, that circulating BDNF level inversely correlates with vascular cell adhesion molecule-1, which is an accepted biomarker of endothelial dysfunction." (PMID 30767081, 2019). "Therefore, we hypothesized that in patients with PAD, circulating VCAM-1 might be elevated due to its function in mediating adhesion of immune cells to the vascular endothelium in the process of endothelial dysfunction and inflammation, and, therefore, applicable as a diagnostic biomarker." (PMID 30535754, 2019). "We examined the ability of metformin + esomeprazole to rescue TNF-α induced vascular cell adhesion molecule-1 (VCAM-1) and Endothelin-1 (ET-1) expression, leukocyte adhesion (markers of endothelial dysfunction)." (PMID 29466360, 2018). "Overexpression of Orai1 potentiates the expression of ICAM-1 and VCAM-1, silencing of TRPC1 attenuates cisplatin-induced ICAM-1 expression and endothelial dysfunction and overexpression of TRPC3 enhances TNFα-induced VCAM-1 expression." (PMID 29772843, 2018). "The increased expression of cellular adhesion molecules, such as VCAM-1 and ICAM-1, plays an important role in endothelial dysfunction and is essential to recruiting monocytes from the circulation." (PMID 28153917, 2017). "We have previously suggested a contribution of endothelial dysfunction to the pathophysiology of SCD-related glomerulopathy based on elevated levels of sFLT-1 and soluble VCAM-1 in patients with albuminuria." (PMID 27669006, 2016). "When endothelial dysfunction occurs, the mRNA and protein expression of ICAM-1, VCAM-1, and MCP-1 increases." (PMID 27190988, 2016). "Immunohistochemistry analyses revealed increased VCAM1 protein expression in the aortic root of female LI-IGF-I−/− mice, possibly suggesting endothelial dysfunction/activation in female LI-IGF-I−/− mice." (PMID 26627099, 2016). "At early stages of vascular inflammation, VCAM-1 and ICAM-1 are upregulated in ECs to facilitate leukocyte adhesion to activated ECs and eventually promote endothelial dysfunction." (PMID 27861612, 2016). "At the same time points serotonin and soluble vascular cell adhesion molecule 1 (s-VCAM1), a marker of endothelial dysfunction, were measured." (PMID 27188755, 2016). "When endothelial dysfunction occurs, the expression of ICAM-1, VCAM-1, and MCP-1 in mRNA is upregulated." (PMID 27190988, 2016). "The permanence of the inflammatory condition in the vasculature can induce endothelial dysfunction and activation with an increase in the expression of chemotactic factors and adhesion molecules such as ICAM-1 and VCAM-1." (PMID 26055507, 2015). "Individuals with diabetes tend to exhibit high levels of adhesion molecule markers of endothelial dysfunction – ICAM-1, VCAM-1 and E-selectin." (PMID 25855488, 2015). "A recent report has suggested that endothelial dysfunction in FSGS, which involves increased levels of endothelial cell-derived circulating VCAM-1 and thrombomodulin levels, is largely related to disease activity." (PMID 26266776, 2015). "Certain markers of endothelial dysfunction (ICAM-1 and VCAM-1), inflammation (C-reactive protein) and thrombotic activity (PAI-1) are also reported here for the first time." (PMID 25115868, 2014).
endothelial dysfunction (continued). "Others have found that liraglutide inhibits high-glucose induced endoplasmic reticulum stress, and also TNFα induced markers of endothelial dysfunction such as PAI-1, ICAM-1, and VCAM-1 in human umbilical vein endothelial cells (HUVECs)." (PMID 24835252, 2014). "There were reductions in concentrations of circulating biomarkers of endothelial dysfunction, E-selectin, ICAM-1 and VCAM-1." (PMID 24646518, 2014). "Soluble form of VCAM-1, ICAM-1, and E-selectin are present in plasma and reflect cellular inflammatory status and correlate with endothelial dysfunction." (PMID 24883317, 2014). "The increase of many markers of endothelial dysfunction, including thrombomodulin, von Willebrand factor (VWF) and VCAM-1, has been repeatedly reported in women with PE." (PMID 19587779, 2009). "Much like in IBD, the pathogenic contributions of VCAM-1 in CRC are not limited purely to its ability to bind integrin for cell-to-cell adhesion, but also in downstream signalling pathways involved in endothelial dysfunction and tumour cell survival." (PMID 40095109, 2025). "Additionally, VCAM-1 and ICAM-1, which are markers of endothelial dysfunction, correlate negatively with adiponectin levels, further linking its deficiency to cardiovascular risk in PCOS." (PMID 40385768, 2025). "To evaluate whether NAC protects against oxLDL-induced endothelial dysfunction, we assessed NO levels, eNOS and LOX-1 expression, and pro-inflammatory adhesion proteins, including ICAM-1 and VCAM-1." (PMID 40774821, 2025). "Preclinical studies have shown that metformin regulates endotoxemia-induced endothelial dysfunction and inflammation through the AMPK/KLF2 axis, restoring KLF2 levels reduced by LPS and TNF-α stimulation, and inhibiting VCAM1 expression while reducing inflammatory factors like TNF-α and IL-6." (PMID 41373858, 2025). "Additionally, increased levels of cellular adhesion molecules like E-selectin, ICAM-1, and VCAM-1 in the plasma have been recognized to identify diabetes and CAD-induced endothelial dysfunction." (PMID 40072053, 2025). "Furthermore, incubation with oleate even reduced VCAM-1 and ICAM-1 expression and NF-κB activation, and OA mitigated the hazardous effects of other endothelial dysfunction triggers." (PMID 41465574, 2025). "This immune activation leads to endothelial dysfunction through multiple convergent pathways: direct cytokine‐mediated endothelial activation (increased ICAM‐1, VCAM‐1, E‐selectin expression), anti‐tTG antibody cross‐reactivity with cerebral endothelium, and systemic inflammatory effects." (PMID 40114993, 2025). "For example, the concurrent elevation of adhesion molecules (ALCAM and VCAM1) alongside pro-inflammatory cytokines (TNFRSF1B and OPN) could provide deeper insights into endothelial dysfunction and immune activation in LN." (PMID 40047601, 2025). "Additionally, Protein expression of VCAM1 and ICAM1, known markers of endothelial dysfunction, were also significantly increased by Ng-siRNA, indicating brain endothelial cell activation." (PMID 39367201, 2025). "Specifically, tat-induced endothelial dysfunction is instigated by dysregulation of ROS production and upregulation of interleukin-1 beta (IL-1β), MCP-1, vascular cell adhesion protein-1 (VCAM-1) and E-selectin expression through activation of the NF-κB signaling pathway, as demonstrated on HUVECs." (PMID 41465377, 2025). "Similarly, elevated VCAM-1 levels correlate with both the presence and progression of WMH and lacunar infarcts, emphasizing their role in vascular inflammation and endothelial dysfunction." (PMID 40718100, 2025). "Elevated Non-HDL-C also exacerbates endothelial dysfunction by reducing endothelial nitric oxide synthase (eNOS) activity and stimulating expression of adhesion molecules (VCAM-1, ICAM-1), thereby reinforcing the classic LDL-C–endothelial interaction." (PMID 40708721, 2025).